FH (fumarate hydratase)
Diseases named in the same sentence as FH in open-access papers (continued):
Sharing a sentence is not in itself a finding about the gene and the disease.
cancer (continued). "Hallmark cancer mutations have been observed in TCA cycle genes such as the fumarate hydratase and succinate dehydrogenase, which are characterized by a loss of function resulting in elevated succinate and fumarate levels in some rare cancers." (PMID 29439493, 2018). "Although fumarate accumulation activates a plethora of signalling cascades, our findings suggest that the EMT is a key phenotype of FH-deficient cancer driven caused by fumarate-driven TET-mediated suppression of miR-200." (PMID 27886164, 2017). "Inactivating mutations affecting the mitochondrial succinate dehydrogenase (SDH) complex subunits and fumarate hydratase (FH) are driver mutations in a subset of cancers." (PMID 29354634, 2017). "Germline met proto-oncogene (MET) and fumarate hydratase (FH) alterations are the hallmark of these cancer syndromes, but are infrequent in sporadic cases." (PMID 27993170, 2016). "The association between fumarate/succinate and cancer was noticed by the high rates of fumarate hydratase and succinate dehydrogenase mutations in certain cancers." (PMID 26950159, 2016). "The tricarboxylic acid (TCA) cycle enzymes isocitrate dehydrogenase (IDH), succinate dehydrogenase (SDH) and fumarate hydratase (FH) are mutated in a subset of human cancers, leading to alterations in cell metabolism." (PMID 26472283, 2015). "The accumulation of fumarate in FH-deficient human cancers has been previously linked with the activation of the transcription factor Nrf2 (refs 5, 7), which elicits an antioxidant response and prevents the elevation of ROS to toxic levels in these cells." (PMID 25613188, 2015). "Part of its tumorigenic activity has been attributed to the abnormal accumulation of fumarate, which peaks to high millimolar levels in FH-deficient cancer cells." (PMID 25057353, 2014). "Somatic mutations in SDH and loss-of-function germline mutations in FH have been associated with many cancers." (PMID 24837709, 2014). "While ROS have been shown to stabilize NRF2, FH-deficient cancer cells primarily activate NRF2 by succination and inactivation of KEAP1." (PMID 25671107, 2014). "A candidate gene linking energy homeostasis and cancer would be FH whereby a single inactivating mutation can affect distinct functions encoded by the same gene (cytosolic FH with DNA repair activity and mitochondrial FH with metabolic activity)." (PMID 23555580, 2013). "Fumarate, one of the intermediates of the TCA cycle, is considered to be an oncometabolite that promotes cancer based on the human cases carrying heterozygous germline mutations in the fumarate hydratase (FH) gene." (PMID 23272301, 2012). "The contribution of other NRF2 target gene products to the properties of FH-deficient cancers would be studied in more detail." (PMID 23272301, 2012). "Further analyses in cell lines derived from Fh1−/− MEFs, mouse cystic tissues and FH-associated human cancer demonstrated that activation of the canonical NRF2 antioxidant pathway arose as a direct consequence of FH inactivation." (PMID 22014577, 2011). "This assumption is based on the data on inhibition of HIF1α-oxidizing prolyl hydroxylases by fumarate or succinate in cancer cells with a deficiency of fumarate hydratase and/or succinate dehydrogenase, which results in pseudohypoxia even with normal oxygen content in the medium." (PMID 40071074, 2025). "Mutations in the FH gene, including missense, frameshift, and complete or partial deletions, can cause a decrease in the expression of fumarate hydratase, causing intracellular fumarate accumulation and leading to cancer." (PMID 39160519, 2024). "Finally, and likely the most clinically relevant challenge will be targeting some of the hallmarks of FH loss for cancer therapy." (PMID 37689804, 2023). "The mutation of FH has been identified in a variety of cancers." (PMID 36778129, 2023). "In many cancers, fumaric acid accumulation is caused by fumarate hydratase (FH) mutations." (PMID 36600313, 2023).
cancer (continued). "In addition, cancer cells were indicated to have mutations in the fumarate hydratase (FH) gene, resulting in deficient FH and the accumulation of the fumarate." (PMID 38151790, 2023). "Data about the immunological consequences of FH depletion in cancer are very limited; however, data on the association between fumarate and the immune system in multiple sclerosis and psoriasis indicate that fumarate can also be viewed as an inflammatory regulator." (PMID 35205136, 2022). "The authors found that the reductive glutamine-dependent pathway is the dominant mode in the metabolism of cancer cells (renal carcinoma) derived from patients with mutations in fumarate hydratase, as well as in cells with normal mitochondria subjected to acute pharmacological inhibition of ETC." (PMID 35205619, 2022). "Indeed, a subset of cancers previously considered as type 2 or ’oncocytic pRCC’ are now known to correspond to fumarate hydratase-deficient RCCs." (PMID 35674688, 2022). "Cancer screening was performed in two patient with the FH and ATM mutation." (PMID 35719373, 2022). "Similarly to 2-HG, fumarate and succinate, which are known to accumulate in cancer cells due to their deficiency in FH and SDH enzymes, can compete with α-KG to inhibit TETs." (PMID 35269796, 2022). "The accumulation of mitochondrial metabolites, succinate and fumarate in SDH and FH-deficient cancer inhibits PHD by competing with its substrate α-ketoglutarate and causes the stabilization of HIF-1α in a normoxic condition, creating a pseudohypoxic condition." (PMID 34829708, 2021). "As a result, FH was mutated or copy number varied in 27 cancers." (PMID 34737838, 2021). "In addition, 73 FH mutations were identified across pan-cancer, and all of them (100%) were missense." (PMID 34737838, 2021). "Overall, our results suggested FH is implicated in cancer immunity, particularly in LUAD." (PMID 34737838, 2021). "Results showed that FH was mutated or copy number varied in 27 types of cancer." (PMID 34737838, 2021). "Our results showed FH genome mutation or copy number variation in many types of cancers." (PMID 34737838, 2021). "Corresponding amino acids in human FH of Thr218 and Met432 are located in the core helix, and accumulated fumarate resulting from mutations in this helix have been associated with different types of cancer." (PMID 34656184, 2021). "Moreover, in fumarate hydratase (FH)-deficient cancer cells, accumulated fumarate binds to the glutathione to produce succinated glutathione (GSF)." (PMID 34829892, 2021). "In the current study, we hypothesized that HO-1 inhibition will result in an anti-cancer effect in the examined FH-deficient cell lines." (PMID 31963199, 2020). "The TCA cycle intermediates fumarate and succinate are potent JMJD inhibitors and many cancers harbour mutations in genes encoding fumarate hydratase (FH) and/or the SDH complex, resulting in increased levels of both metabolites, leading to hypermethylation of histones." (PMID 32217072, 2020). "Mutations in SDH and FH have also been associated with cancer and, loss of either of these enzymes leads to vulnerabilities that may be targeted effectively." (PMID 32397535, 2020). "Similarly, fumarate accumulation in FH mutated cells, induced epigenetic regulation of DNA/histone demethylases, with related downstream effect of cancer cells." (PMID 32799884, 2020). "While some of these perturbations have been linked to cancer (e.g., fumarate hydratase mutations, p62 accumulation), further work is needed to determine whether others also play a causal role in tumorigenesis." (PMID 33080927, 2020). "Consequently, FH inactivation takes part in cancer development by inducing a loss of genome integrity." (PMID 31881713, 2019). "•Pyruvate dehydrogenase is inhibited by phosphorylation in FH deficient cancer cells." (PMID 29191787, 2018). "Loss of FH and fumarate accumulation may play a critical role in aggressive features of cancer cells." (PMID 30671168, 2018).
cancer (continued). "Importantly, fumarate hydratase deficient cancer cells and multiple cancer cell lines with reduced amounts of mtDNA were resistant to ONC201." (PMID 29719618, 2018). "The other TCA enzyme where inactivating mutations of which are linked to cancer is FH." (PMID 28785398, 2017). "Other enzymes such as fumarate hydratase (FH) have also found to be mutated in other cancers." (PMID 28932704, 2017). "Many of the recent advances in our understanding of mitochondrial metabolic plasticity have been acquired through investigations of cancer‐associated mutations in metabolic enzymes, including succinate dehydrogenase, fumarate hydratase, and isocitrate dehydrogenase." (PMID 27196610, 2016). "Research with cancer cells has shown that defects in TCA cycle enzymes, such as succinate dehydrogenase, fumarate hydratase, and isocitrate dehydrogenase, cause inherited benign or malignant tumours by altering DNA and histone modifications thereby causing transcriptional dysregulation." (PMID 27425144, 2016). "FH-deficient cancer cells display pseudo-hypoxia with aberrant activation of HIF1α." (PMID 25671107, 2014). "The unexpected finding that mutations in the TCA cycle enzymes succinate dehydrogenase (SDH) and FH, predispose to cancer, potently rekindled the field of cancer metabolism and promoted investigations of the link between aberrant metabolism and cancer formation." (PMID 24280230, 2013). "Mutation of these genes in cancer leads to a buildup of their substrates; fumarate and succinate in the case of FH and SDH mutations, or conversion of their regular substrate to a new “oncometabolite” in the case of mutant IDH1/IDH2 converting isocitrate to 2-hydroxyglutarate." (PMID 24350057, 2013). "The combination of dysregulation in these metabolic regulators and the truncated Krebs cycle may underlie the metabolic reprogramming in the FH null cancer cells, which is distinct from the metabolic reprogramming of other cancer cell types." (PMID 23967283, 2013). "This cancer can develop when the tumor suppressor gene fumarate hydratase (FH) is mutated." (PMID 24027532, 2013). "The inhibition of HO-1 is effective for the suppression of FH-deficient cancers." (PMID 23272301, 2012). "Disruption of this cycle in FH deficiency reduces oxidative ATP production and forces a compensatory reliance on glycolysis, a less efficient pathway that increases lactate production—an adaptive shift often referred to as the Warburg effect and frequently documented in cancer biology." (PMID 41374387, 2025). "Importantly, patients with a germline FH mutation should be advised about the risk of cancer." (PMID 37663422, 2023). "However, others have suggested that fumarate accumulation due to fumarate hydratase loss-of-function mutation or direct administration, could directly initiate or expedite ferroptosis in several types of cancer cells." (PMID 37834044, 2023). "The increased number of dying cells due to impaired DNA repair in FH-deficient cells is probably associated with innate and adaptive immune responses, but more research is needed to assess the association between metabolic disturbances in cancer cells and DNA damage response." (PMID 35205136, 2022). "SIRM has been applied most heavily in cancer research, where it has been used to elucidate alterations in metabolic networks associated with different cancers, as well as rare somatic mutations in isocitrate dehydrogenase, and germline lesions in fumarate hydratase and succinate dehydrogenase." (PMID 33302448, 2020). "Notably, FH-mutated cells require a constant supply of exogenous arginine to keep the urea cycle active and are disabled when arginine is short-of-supply, thereby creating a cancer-specific vulnerability." (PMID 32799884, 2020).
cancer (continued). "Our work provides a novel approach to investigate how post-translational modifications of enzymes regulate metabolism and could have important implications for understanding the metabolic transformation of FH-deficient cancers with potential clinical applications." (PMID 29191787, 2018). "Succinate dehydrogenase (SDH), fumarate hydratase (FH), and isocitrate dehydrogenase (IDH) are enzymes that are frequently mutated in various cancers." (PMID 40919131, 2025). "In cancer, mutations in TCA cycle enzymes, including succinate dehydrogenase (SDH), fumarate hydratase (FH), and isocitrate dehydrogenase (IDH), are unifying features of the accumulated TCA cycle intermediates." (PMID 41551149, 2025). "Several enzymes involved in the TCA cycle—such as succinate dehydrogenase (SDH), fumarate hydratase (FH), and isocitrate dehydrogenase (IDH)—have been implicated in cancer development." (PMID 40365984, 2025). "Mutations in fumarate hydratase (FH) and succinate dehydrogenase (SDH), which lead to accumulation of fumarate and succinate, predispose patients to various cancer types." (PMID 40523311, 2025). "Downregulation of succinate dehydrogenase (SDH) and fumarate hydratase (FH) activities, which are common hallmarks of cancers, results in the accumulation of succinate, inhibition of PHD activity and induction of HIF-1α." (PMID 40264757, 2025). "Mutations in fumarate hydratase (FH), an enzyme of the Tricarboxylic Acid (TCA) cycle, also lead to hereditary and sporadic forms of cancer that establish novel paradigms of oncometabolism." (PMID 40075667, 2025). "Mutations of fumarate hydratase (FH), succinate dehydrogenase (SDH), and nicotinamide N-methyltransferase (NNMT) can also lead to methylation changes in cancer cells." (PMID 40438494, 2025). "The dominant mutation of succinate dehydrogenase (SDH) and recessive mutation of fumarate hydratase (FH) are enzymes involved in the TCA cycle that regulate HIF transcription factors and are often mutated in some cancers." (PMID 39996906, 2025). "Recent research has identified FH as a tumor suppressor gene involved in cancer development and progression, highlighting its potential as a therapeutic target." (PMID 41008787, 2025). "Generally, FH aberrations (mutations, CNA, and 1q arm level) prevalence in BC is lower than in other cancer types." (PMID 41008787, 2025). "As for other cancer types, FH was regarded as the gene responsible for HLRCC, SDH was found to be associated with familial renal cancer, and MET was thought to be correlate with hereditary pRCC." (PMID 40933888, 2025). "In the future, the response of s-FH-Ab levels to treatment and how autoantibodies change during cancer recurrence must be analyzed." (PMID 38791507, 2024). "Nonetheless, further research is required to decode the specific mechanisms through which FH regulation in TAMs within the pan-cancer microenvironment influences their inflammatory effects." (PMID 38185636, 2024). "Here, we report 9 out of 24 patients with non-contributory family history, harboring germline heterozygous deleterious mutation in well-known cancer predisposing genes (CHEK2, RAD51C, BRCA2, FANCA, RET, FH, and BAP1)." (PMID 38700789, 2024). "Low FH levels are thought to influence cancer cell progression through these multiple step-by-step mechanisms, and FH plays an important role in energy acquisition and cancer progression." (PMID 38791507, 2024). "Low FH expression has been shown to activate oncogenic signaling cascades in cancer cells and promote metastasis, and patients with low FH expression have a shorter overall survival." (PMID 39403185, 2024). "In the context of cancer, mutations in ncDNA genes can affect the expression or activity of TCA cycle-related enzymes, such as succinate dehydrogenase (SDH), fumarate hydratase (FH), and isocitrate dehydrogenase (IDH), which have a direct effect on OXPHOS." (PMID 38255314, 2024).
cancer (continued). "Fumarate hydratase (FH) is an important metabolic enzyme in the tricarboxylic acid (TCA) cycle, and the loss of FH can act as a cancer driver." (PMID 38398104, 2024). "All five genes (BAP1, FANCA, RET, FH, and RAD51C) are well-known cancer predisposing genes with incomplete penetrance and variability of expression." (PMID 38700789, 2024). "It is found that ER stress can regulate crucial enzyme (MDH2 and FH) activities of metabolic cascade in cancer cells, boosting aerobic respiration to attenuate the Warburg effect and promote cell apoptosis." (PMID 38483955, 2024). "Fumarate hydratase (FH) is an enzyme of the Tricarboxylic Acid (TCA) cycle whose mutations lead to hereditary and sporadic forms of cancer." (PMID 37689804, 2023). "These metabolites or enzymes such as isocitrate dehydrogenase (IDH), fumarate hydratase (FH), succinate dehydrogenase (SDH) and α-ketoglutarate dehydrogenase (α-KGDHC) are often mutated or deregulated in human cancers." (PMID 36778129, 2023). "It has previously been reported that mitochondrial function is essential for cancer cell viability and that mutations in SDHA, FH, and IDH1 can change mitochondrial metabolism and allow cancer cells to adapt to changing environments." (PMID 37190292, 2023). "JUN, CXCR4, and WNT5A were the top three interaction DEGs in pathways in cancer; H6PD, FH, and ACO2, which associate with glucose metabolism, were the top three interaction DEGS in metabolic processes." (PMID 37601754, 2023). "Several oncometabolites, such as 2-hydroxyglutarate (2HG), succinate, and fumarate, accumulate due to mutations in nuclear-encoded mitochondrial enzyme genes, including isocitrate dehydrogenase (IDH) 1 and 2, SDH, and fumarate hydratase (FH), in human cancers." (PMID 37525297, 2023). "In last decades, mutations identified in IDH1 and IDH2, and a few other metabolic genes, such as succinate dehydrogenase (SDH) and fumarate hydratase (FH), have provided compelling evidence for metabolic alteration in human cancer development and progression." (PMID 37296846, 2023). "Some examples found in various types of cancer are loss-of-function mutations of the iron-sulfur B subunit of the succinate dehydrogenase complex (SDHB) and fumarate hydratase (FH) with increased levels of fumarate and/or succinate." (PMID 37179826, 2023). "General attention paid to mitochondrial nuclear-encoded gene mutations has greatly emerged since the defects of fumarate hydratase, succinate dehydrogenase, isocitrate dehydrogenase 1 (IDH1), and IDH2 in cancer cells were established." (PMID 36557887, 2022). "In such a setting, only cancer-specific TAAs and TAAs with a somewhat promiscuous pattern of serological reactivity (e.g., FH) are to be identified." (PMID 35203677, 2022). "The mutations in the genes of isocitrate dehydrogenase (IDH1/IDH2) 8-13 and succinate dehydrogenase (SDHA/SDHB/SDHC/SDHD) 14-21 families, and fumarate hydratase (FH) 22 were found in many types of human cancers." (PMID 36168622, 2022). "In the TCA cycle, alteration of FH determines lots of changes in cancer cellular metabolism such as glycolytic switch towards ROS." (PMID 35096270, 2022). "Mutations in genes encoding enzymes of the TCA cycle have been associated with cancer progression, especially succinate dehydrogenase (SDH), fumarate hydratase (FH), and isocitrate dehydrogenase (IDH)." (PMID 35831624, 2022). "Our study has also identified alterations in HLRCC ULMs that have been explored in relation to therapeutic interventions for cancer treatment as well as in FH mutant backgrounds." (PMID 33931688, 2021).